NLK (nemo like kinase)
Diseases named in the same sentence as NLK in open-access papers (continued):
Sharing a sentence is not in itself a finding about the gene and the disease.
cancer (25 papers, 2013 to 2025). A tumor composed of atypical neoplastic, often pleomorphic cells that invade other tissues. "Other than the NLK/c-Myb pathway, additional mitogenic cascades have been found to be associated with NLK function in cancer." (PMID 23935942, 2013). "However, due to different types of cancer and their associated cellular environments, the role of NLK may vary or even be opposite in different types of cancer." (PMID 39097735, 2024). "The interaction between heat shock protein 27 (HSP27) and NLK mediated the nuclear localisation and protected the cancer cells from apoptosis." (PMID 33276680, 2020). "The mitogen-activated protein kinase (MAPK) member, NLK is involved in a variety of signaling pathways as well as in several types of cancer." (PMID 32605309, 2020). "NLK, which belongs to the mitogen-activated protein kinase family, is a vital regulator of various cancer types." (PMID 31294654, 2019). "Anti-tumorigenic effects of NLK have been characterized in different cancer types, but relatively little is understood about the role of NLK in GBM." (PMID 26023737, 2015). "Meanwhile, metformin can be a potential drug for NSCLC, specifically through inhibition of cancer cell proliferation, down-regulation of NLK, and reduction of the cancer stem cell population." (PMID 26503334, 2015). "Aberrant expression of NLK has been reported in human cancer including colon, hepatocellular, and prostate carcinomas." (PMID 26503334, 2015). "Previous research has shown that an enzyme called Nemo-like kinase (or NLK for short) regulates the normal androgen receptor in cancer cells." (PMID 26308581, 2015). "NLK is critical for cancer cell cycle progression, and tumorigenesis in NSCLC, NLK knockdown, and metformin treatment inhibit cancer cell proliferation and stemness." (PMID 26503334, 2015). "After NLK silencing, the proportion of cancer cells in the G1 phase was significantly increased in both cell lines, and those in the S phase was significantly decreased concomitantly." (PMID 26503334, 2015). "Taken together, our findings indicate that cancer stem cell stemness is significantly decreased by NLK silencing or metformin treatment." (PMID 26503334, 2015). "The nuclear localization of NLK was mediated through direct interaction with Heat shock protein 27 (HSP27) which further protected cancer cells from apoptosis." (PMID 24816797, 2014). "Seeking an explanation for NLK inactivation in cancer cells, we performed a MALDI-TOF mass spectrometry analysis." (PMID 24816797, 2014). "Immunohistochemical staining of human breast tissue, cancerous and normal, showed NLK to be localized in the nuclei of cancer cells, while normal breast tissue contained cytosolic NLK." (PMID 24816797, 2014). "As we expected, the relative abundances of NLK and c-Myb appeared to be inversely correlated in the normal human breast epithelial and the two cancer cell lines." (PMID 23935942, 2013). "Second, Nemo-like kinase (NLK), Polo-like kinase 4 (PLK4) and TTK (alias MPS1) were identified in synthetic lethal screens in PTEN-deficient cancer cells and may warrant further investigation in LMS." (PMID 38473300, 2024). "Thus, stress activates NLK-Yap1-CXCL2/5 signaling in 14-3-3ζ+++ cancer cells to instigate PSCs/fibroblasts which in turn support cancer cell proliferation and survival." (PMID 39468013, 2024). "Together these results indicate that, in 14-3-3ζ+++ cancer cells, low-nutrient- or chemotherapy-induced stresses stabilize NLK protein to induce pS128-Yap1 that releases 14-3-3ζ-bound Yap1 for nuclear translocation and activation, leading to CXCL2/5 upregulation." (PMID 39468013, 2024). "Furthermore, both knockdown of NLK and metformin treatment significantly reduced cancer stem cell stemness." (PMID 26503334, 2015).
cancer (continued). "Meanwhile, cancer cell self-renewal and stemness were inhibited by NLK knockdown." (PMID 26503334, 2015). "We propose that in different tissue-derived carcinomas, NLK may be differentially activated and may act through diverse pathways to influence the expression of various target genes resulting in distinct biological behaviors." (PMID 26503334, 2015). "To determine whether loss of NLK in the cytosol would have an oncogenic effect, we examined proliferation and survival of cancer cells in the presence of wildtype or catalytically inactive NLK mutants." (PMID 24816797, 2014). "To find an explanation for the inactivation of NLK in cancer cells, we explored whether any putative interaction partners for NLK might hold NLK in an inactive form in the nucleus of cancer cells." (PMID 24816797, 2014). "Moreover, the association of NLK with HSP27, which was identified as a novel binding partner for NLK, protected the cancer cells from apoptosis." (PMID 24816797, 2014). "One study delineated how metformin exerts its repressive impact on cancer cell proliferation and stemness in NSCLC by pinpointing Nemo-like kinase (NLK) as a candidate." (PMID 38068934, 2023). "On the other hand, “hub genes” of four other modules contain POU2F3 (↑), CENPH (↑), PCSK6 (↑) and HERC2 (↑), BCAR3 (↑), DOHH (↑), NLK (↑), SCN2A (↑), CACNA2D3 (↓) and CTNND2 (↓), which were commonly reported related to cancer." (PMID 27602771, 2016). "The other novel translocation case did not disrupt a known cancer gene but occurred close to NLK (Nemo‐like kinase), a serine/threonine‐protein kinase, which has been associated with the noncanonical Wnt and MAPK signaling pathways." (PMID 31943436, 2020). "Intriguingly, in our study metformin treatment reduces NLK expression, arrests the cell cycle arrest and potentiates anti-proliferation selectively in cancer cells but not the normal lung epithelial cells." (PMID 26503334, 2015). "Our results suggest that HSP27 recognizes and binds to the non-phosphorylated form of NLK, which is exclusively located in the nuclei of cancer cells." (PMID 24816797, 2014). "To test the hypothesis that HSP27 is responsible for sustained nuclear localization of NLK, we reduced the level of HSP27 in cancer cells, by using two different siRNA oligos, and investigated NLK localization." (PMID 24816797, 2014).
neurodegenerative disease (2 papers, 2020 to 2025). A disorder of the central nervous system characterized by gradual and progressive loss of neural tissue and neurologic function. "NLK has been shown to be expressed at high levels in the nervous system and brain; however, its function regarding neurological development and neurodegenerative diseases is not well understood." (PMID 33276680, 2020). "Our findings suggest that NLK is a promising therapeutic target for neurodegenerative diseases." (PMID 40553568, 2025).
genetic disorders (1 paper, 2021). "In particular, kinases that are deregulated in multiple genetic blood disorders, for example NLK being activated in ribosomopathies, offer particular value as common targets to multiple genetic disorders." (PMID 34681039, 2021).
heart disease (1 paper, 2016). "Taken together, these observations indicate that NLK is a maladaptive signaling kinase in the heart that mediates disease, hence it represents a novel target for potential pharmacologic intervention in treating human heart disease, and as such, selective kinase inhibitors should be developed." (PMID 27764156, 2016).
infection (1 paper, 2019). The state of being infected such as from the introduction of a foreign agent such as serum, vaccine, antigenic substance or organism. "Fortunately, one evolutionarily conserved serine/threonine protein kinase, NLK, was found to exert strong inhibitory effects on the production of antiviral cytokines after the infection of cells with SeV." (PMID 31324787, 2019). "In contrast, NLK bound strongly to MAVS after exposure to the virus in the later phase of infection." (PMID 31324787, 2019). "Interestingly, infection of cells with SeV resulted in the redistribution of NLK into mitochondrial and peroxisomal fractions." (PMID 31324787, 2019). "Moreover, the depletion of NLK promotes antiviral effects and increases the survival times of mice after infection with VSV." (PMID 31324787, 2019). "Antiviral response analyses using flow cytometry and plaque assays consistently demonstrated that NLK reconstitution in NLK−/− HCT116 cells significantly restored the frequency and viral titer of infected GFP-positive cells after VSV-GFP infection." (PMID 31324787, 2019).
NLK also shares sentences with these, for which no sentence is quoted: oral squamous cell carcinoma (2 papers); osteosarcoma (2); anemia (1); cervical cancer (1); gastric cancer (1); gastric tumors (1); metastatic melanoma (1); myeloma (1); nasopharyngeal carcinoma (1); papillary renal cell carcinoma (1); rectal cancer (1); small cell lung carcinoma (1).